FAP (fibroblast activation protein alpha)
Diseases named in the same sentence as FAP in open-access papers (continued):
Sharing a sentence is not in itself a finding about the gene and the disease.
tumor (continued). "FAP+ CAFs modulate the tumor microenvironment through secretions such as C-C motif chemokine ligand 1, 2 and 5 (CCL1, CCL2, CCL5) and CXCL12 in HCC." (PMID 31540435, 2019). "Despite in vitro activity observed, the injection of the FAP-CAR T cells only elicited limited in vivo anti-tumor effect." (PMID 30809507, 2019). "With the specific expression of the fibroblast activation protein-alpha (FAP-a), Carcinoma-associated fibroblasts (CAFs) are the main cell populations in the remodeled tumor stroma." (PMID 31921678, 2019). "Germline knockout of FAP resulted in increased disorganized collagen deposition in colorectal and pancreatic tumors with diminished tumor growth via indirect effects on tumor cell proliferation and decreased neovascularization." (PMID 30726287, 2019). "In one study, where human MPM tumor samples and fibroblast samples were shown to be positive for FAP by immunohistochemistry, FAP CAR T cells efficiently killed MPM cells in vitro." (PMID 30804938, 2019). "Mice that were depleted of FAP+ cells and harboring subcutaneous tumors showed tumor regression after treatment with a vaccine‐based immunotherapy." (PMID 30003190, 2018). "In this respect, the limiting factor for the detection of tumor lesions is the degree of FAP expression within the tumor." (PMID 29626120, 2018). "In this study, stromal FAP levels correlated with adverse clinic-pathological characteristics in GC, including larger tumor diameter, poorly tumor differentiation degrees, and advanced TNM stage." (PMID 30419872, 2018). "High levels of fibroblast activation protein (FAP) have been correlated with tumor size, high grade, high stage and shorter survival in CCRCC, both in primary tumors and in its paired metastases." (PMID 30518081, 2018). "In vivo administration of a FAP enzyme inhibitor, Talabostat, in tumor-bearing mice results in tumor regression and upregulation of specific chemokines and cytokines that induce an anti-tumor immune response." (PMID 29868579, 2018). "This study also provides a potential therapeutic approach using SnMP, a drug that has already been used in the clinic, to target the ability of FAP+ HO-1+ TAMs to facilitate tumour cell intravasation and spread of the disease." (PMID 30054470, 2018). "FAP expression correlated with the tumor diameter (P = 0.024), tumor differentiation degrees (P = 0.002), and TNM stage (P = 0.001), but not correlated with age and gender (P > 0.05 for all)." (PMID 30419872, 2018). "As both IL-6 and collagen are highly abundant in healing wounds, these findings suggest that tumours can mimic a wound-like microenvironment which maintains an FAP+ HO-1+ TAM phenotype." (PMID 30054470, 2018). "In particular, expression of Col1a1, the gene for type 1 collagen and the substrate for FAP, was significantly higher in the 4T1 tumours." (PMID 30054470, 2018). "We addressed this task by developing a small-molecule radiopharmaceutical based on a FAP-specific inhibitor and were able to show specific uptake, rapid internalization, and successful imaging of tumors in animal models and tumor patients." (PMID 29626120, 2018). "It has been reported that transfer of murine T cells transduced with FAP-CAR construct can affect tumor cell growth increasing the CD8+ T cell response." (PMID 29515580, 2018). "In tumor cell lines, NG-641 selectively secretes functional FAP-TAC molecules, as determined in cocultures of FAP+ fibroblasts and PBMC-derived T cells." (PMID 30400822, 2018). "This study has started to shed light on the contextual origin of FAP+ HO-1+ TAMs and their exploitation by the tumour to facilitate metastatic spread of the disease." (PMID 30054470, 2018). "As FAP expression was associated with EGR1 upregulation, we assessed the presence of nuclear EGR1 in TAMs in 4T1 tumours grown in WT and Il6−/− mice and found a significant reduction of nuclear EGR1 in the TAMs of Il6−/− mice." (PMID 30054470, 2018).
tumor (continued). "As a therapeutic target, FAP has been utilized as a useful cancer vaccine in inhibiting tumor growth and increasing cytotoxicity." (PMID 30031396, 2018). "We have demonstrated IL-6 to be a key regulator of the FAP+ HO-1+ macrophage phenotype, and this cytokine is also expressed directly by the macrophages in 4T1 tumours." (PMID 30054470, 2018). "As such, FAP has emerged as a potential therapeutic target to abate the tumor promoting effects of CAFs." (PMID 30103384, 2018). "There were also significantly fewer pulmonary metastases in mice bearing E0771 tumours that were devoid of FAP+ HO-1+ TAMs when compared to mice bearing 4T1 tumours." (PMID 30054470, 2018). "The F4/80+ TAMs present in these tumours represented 10.8 ± 3.3% of all live tumoural cells and expressed FAP, alongside the macrophage/TAM markers CCR2, CD11b, CD14, MHCII, IL4-R and MMR, with a low expression of the dendritic cell marker CD11c." (PMID 30054470, 2018). "In OC, FAP promoted HO-8910PM tumor cell proliferation, invasion and migration via interactions with integrin α3β1 and urokinase-type plasminogen activator receptor (uPAR) signaling complex." (PMID 30103384, 2018). "An additional factor involved in CAF-tumor cell cross-talk is the fibroblast activation protein (FAP)." (PMID 30103384, 2018). "Similar to myofibroblasts in wounds or fibrotic tissues, tumor-associated fibroblasts are known to overexpress ACTA2, FAP and PDGFRB." (PMID 30473751, 2018). "The expression of FAP by the macrophages was a stable phenotype in this model, and was constant during the growth of 4T1 tumours." (PMID 30054470, 2018). "FAP is expressed in NK cells after activation to attenuate cytotoxicity and can be inhibited to enhance anti-tumor immunity." (PMID 30400822, 2018). "Vaccines targeting FAP-expressing cells significantly suppressed tumor growth by eliciting CD8+ or a combined CD8+ and CD4+-T cell response respectively." (PMID 30103384, 2018). "FAPI-02 rapidly internalizes into FAP-expressing cells and shows high tumor uptake rates in both tumor-bearing mice and patients with metastasized epithelial carcinomas." (PMID 29626120, 2018). "In the present work, we reported a method to isolate FAP+ CAFs, an important cell population found in tumor tissue, through twice collagenase type IV digestion and magnetic cell separation." (PMID 28890895, 2017). "Preclinical studies have demonstrated that CAR T cells targeted to murine FAP have anti-tumor efficacy in subcutaneous MPM models with minimal toxicity." (PMID 28862644, 2017). "FAPα showed immunosuppressive functions in a tumor microenvironment, and depletion of FAPα in stromal cells suppressed the growth of solid malignant tumors." (PMID 28415791, 2017). "Using a weakly immunogenic and highly desmoplastic tumor, pancreatic ductal adenocarcinoma, Lo and colleagues demonstrated that FAP-CAR T-cells inhibited tumor stromagenesis, reduced tumor vascular density and disrupted spatial orientation of tumor cells." (PMID 28331617, 2017). "Since FAP-α is excessively present in tumor tissue, the ferritin-based fluorescence-tagged peptide on the probe will become cleaved by the FAP-α to release the fluorophore and be detected." (PMID 28492519, 2017). "IHC staining of mice tumor biopsies revealed increased expression of fibronectin and FAP, and decreased expression of E-cadherin and VCAM-1 after exosomes treatment." (PMID 28178689, 2017). "Since the tissue distribution of FAP-specific monoclonal antibody was encouraging, investigators have suggested their use as effective vehicles of other therapeutics to the tumor site." (PMID 29072623, 2017). "The immunohistochemical staining for mice tumor biopsies also revealed increased expression of fibronectin and FAP, along with decreased expression of E-cadherin and VCAM-1 after exosomes treatment." (PMID 28178689, 2017). "FAPα-positive cells in tumor microenvironment can produce high levels of inhibitory factors such as TGF-β, IL-6, and IL-10." (PMID 28881756, 2017).
tumor (continued). "Given the potential for multi-modal anti-tumor effects of FAP targeting, rational and interesting combinations for future immunotherapeutic approaches include anti-stroma CAR T-cells with either anti-tumor CAR T-cells or checkpoint blockade." (PMID 28331617, 2017). "The FAPα expression was very low in tumor because only the CAFs expressed FAPα but tumor cells didn’t when the tumor consisted of most the tumor cells." (PMID 28415791, 2017). "Even if T-cell persistence was limited, an improved response was achieved by co-injecting FAP-specific and tumor-specific T-cells." (PMID 28331617, 2017). "In MPM, two such candidate target TAAs are currently being investigated in clinical trials: mesothelin, which is overexpressed on the tumor cells, and fibroblast activation protein (FAP) that is overexpressed on tumor stromal cells." (PMID 28862644, 2017). "In the CAF compartment, pre-clinical transgenic models have demonstrated that FAP regulates collagenase activity, and is important for angiogenesis and tumor growth." (PMID 28966935, 2017). "FAP, α-SMA, FSP1, and PDGFR are not only markers that have important role in cancer-associated fibroblasts but also essential for the proliferation of tumor cells and stimulating metastasis of tumors." (PMID 28890895, 2017). "While there is strong interest to develop FAP targeting anti-cancer strategies for the clinic, it is of concern that studies looking at off-tumour effects of FAP-targeting regimens have yielded mixed results." (PMID 28158223, 2017). "This was a contradictory conclusion according to extensive evidence showing that high expression of FAPα in tumor tissue." (PMID 28415791, 2017). "To evaluate FAPα expression in tumor tissues, we conducted immunohistochemistry with an antibody against human FAPα using prepared paraffin sections from pathological archives." (PMID 28415791, 2017). "The degree of K19 and EpCAM expression was well correlated with tumor stromal FAP expression (P = 0.042 and P = 0.004, respectively), and the degree of CD133 expression was well correlated with tumor stromal α-SMA expression (P = 0.005)." (PMID 29245907, 2017). "The conditional depletion of the FAP in CAFs, hence, restored the immune surveillance (that is, anti-tumor) effect not only of the transplanted tumor, but also of an autochthonous model of PDAC." (PMID 28753978, 2017). "RG7368 was found to induce potent tumor killing in a FAP-dependent manner, and to inhibit tumor growth in vivo." (PMID 31548531, 2017). "The depletion of FAPα-positive cells in LL2 Lewis lung cancer mice rescued the immune response against tumor." (PMID 28881756, 2017). "It has been reported that FAP possess serine protease activity and is positively correlated to tumor malignancy." (PMID 29100326, 2017). "Our results indicated the circulating FAPα was more influenced by the physiologic source than the FAP which expressed in tumor." (PMID 28415791, 2017). "Reduced tumor progression is also achieved by targeting FAP, an antigen that is selectively expressed on fibroblasts present in tumors or at sites of chronic inflammation or wound healing." (PMID 26943036, 2016). "Targeting FAP α genetically with vaccines, with antibodies, or with pharmacological agents, impairs tumor progression in several preclinical cancer models." (PMID 26985769, 2016). "On the contrary, FAP depletion inhibits tumor cell proliferation indirectly by increasing collagen accumulation, decreasing myofibroblasts in number, and decreasing blood vessel density in tumors." (PMID 27018053, 2016). "In this section we will focus on the clinical and preclinical attempts at employing FAP α-targeted treatment strategies and its prospects in tumor therapy." (PMID 26985769, 2016). "In mouse tumor models, FAP-/- and FAP enzymatic inhibition slowed tumor growth, increased stromal collagen content, and decreased collagen fibril organization in the tumor stroma compared to tumor tissues isolated from FAP+/+ mice." (PMID 26934296, 2016).
tumor (continued). "For example, in PDA, FAP+ stromal fibroblasts secrete SDF1 that binds tumor cells to suppress T cells." (PMID 27087446, 2016). "Depleting FAP+ tumor stromal cells significantly increased the overall Trp-1-specific CD8+T cell response in blood (p=0.038, area under the curve); differences were more pronounced at later time points, i.e. on days 35 and 50 after vaccination." (PMID 26943036, 2016). "It has been shown previously that FAP+ stromal cells suppress tumor-specific immune responses and FAP+ cell depletion enhances tumor infiltration by T lymphocytes." (PMID 26943036, 2016). "Only 2% of the tumor cells in this model express FAP α; however, when all FAP α expressing cells (stromal and cancerous) are destroyed, the tumors begin to die rapidly." (PMID 26985769, 2016). "In this article, we will review the role of FAP α in tumor development, discuss FAP α as a potential target, and examine its immunotherapeutic benefits." (PMID 26985769, 2016). "Therapeutic strategies targeting FAP α, a membrane-bound serine protease of the prolyl oligopeptidase family that is expressed on CAFs within the tumor stroma, offer another tumor treatment option." (PMID 26985769, 2016). "FAP expression in metastases showed similar correlations with these variables (with the exception of tumor grade), but also correlated with higher tumor diameter." (PMID 28033421, 2016). "Previous studies have shown that depleting fibroblast activation protein (FAP)-expressing stromal cells reduces tumor progression and concomitantly increases tumor antigen (TA)-specific T cell responses." (PMID 26943036, 2016). "CXCL12 is the reason for immune suppression, while abrogation of FAP α positive cells permits immune inhibition of tumor growth and enhances the efficacy of constructed immunotherapeutic antibodies." (PMID 26985769, 2016). "Adoptively transferred mouse T cells transduced with this FAP-CAR construct inhibited the growth of several types of transplanted tumors through an increase in the CD8-mediated anti-tumor response." (PMID 27834810, 2016). "In a FAP α-positive tumor model, the FAP ατ-MT vaccine elicited an antitumor response that was similar to systemic treatment with the FAP α τ vaccine plus 1-MT." (PMID 26985769, 2016). "The finding that FAP-cleaved collagen enhances SR-A-mediated macrophage adhesion suggests that SR-A-expressing TAMs should be enriched in areas of tumor where TAFs are abundant." (PMID 26934296, 2016). "In vitro studies have shown that stromal cells isolated from both breast and pancreatic tumors can create increasingly aligned fibronectin matrices in a syndecan-1 or FAP-dependent manner respectively, which facilitate tumor cell motility." (PMID 26716418, 2016). "Images of tumor sections demonstrating the localization of the liposomal fluorescence in FAP-expressing tumor cells and myofibroblasts are also presented." (PMID 27642620, 2016). "Such strategies involve; the development of anti-FAP antibodies conjugated to cytotoxic drugs, utilising the enzymatic activity of FAP to activate pro-drugs in the vicinity of the tumour, and vaccines targeted against FAP." (PMID 26784251, 2016). "FAP is a multifunctional protein that regulates tumor growth and invasiveness through mechanisms that are dependent and independent of its catalytic activity." (PMID 28033421, 2016). "Reduction of FAP would thus be expected to remodel the composition of the tumor infiltrates and thereby the cytokine/chemokine milieu." (PMID 26943036, 2016). "Vaccines targeting FAP α provide another therapeutic strategy that takes advantage of the restricted distribution of FAP α in tumor sites." (PMID 26985769, 2016). "The percentage of FAP+ cells in tumor suspensions from Bay60-6583-treated mice versus control mice was also determined by flow cytometric analysis." (PMID 27590504, 2016).
tumor (continued). "To assess if the FAP vaccine was likely to influence tumor progression, we analyzed FAP+ tumor stroma cells from BrafCA/+Ptenlox+/lox+mice that upon treatment with 4-hydroxyltamoxifen (4-HT) developed tumors." (PMID 26943036, 2016). "In our study, FAP was also significantly expressed in nodal CAFs, suggesting that microenvironments in mCCRCC are similar in primary tumor and in lymph nodes." (PMID 28033421, 2016). "A number of studies have shown that FAP- positive CAF promote tumor growth by inducing tumor immune evasion and tumor stromagenesis and vascularization, making FAP a potential therapeutic target in cancer." (PMID 27590504, 2016). "Serine protease fibroblast activation protein (FAP) promotes tumor growth in an endogenous mouse model of lung cancer driven by the K-rasG12D mutant." (PMID 27018053, 2016). "Tumor specimens were obtained from both primary lesion (n = 59) and metastases (n = 54) and FAP expression was immunohistochemically analyzed." (PMID 28033421, 2016). "Here, we show for the first time, to the best of our knowledge, a role for A2BR in promoting the activation of FAP-α positive tumor stromal cells." (PMID 27590504, 2016). "Numbers of Tregs declined upon immunization with either vaccine regimen, indicating that this was unrelated to FAP but more likely reflected the effect of enhanced immune response within the tumor upon vaccination with Ad vectors." (PMID 26943036, 2016). "FAP immunostaining was primarily localized on the cell membrane and in the cytoplasm of tumor cells and CAFs, as well as occasionally in the gland lumens." (PMID 25775399, 2015). "Since there were a large number of FAP-positive (CAF) cells in the tumor, we examined the effect of this antibody on the number of FAP-positive cells." (PMID 26597716, 2015). "Staining with various antibodies was used to evaluate the FAP expression levels and expression status in tumor cells and/or in stroma, although four studies used antibody ab53066, and another four studies used antibody D8." (PMID 25775399, 2015). "We detected IDO expression in regions of B16 tumor tissue and FAPα expression in fibroblasts within the tumor stroma." (PMID 26305550, 2015). "Reports continue to accumulate evidence suggesting that FAP, which is an important marker for CAFs, plays a predominant role in the progression of many tumor types." (PMID 25775399, 2015). "Tumor cells were transfected with a recombinant murine FAP plasmid using the cationic lipid, DOTAP, and were irradiated to prevent their replication and to enhance antigen presentation." (PMID 26394925, 2015). "Planting FAPα-silenced SKOV3 cells in a xenograft mouse model resulted in significantly decreased tumor growth." (PMID 25593080, 2015). "This suggests FAPαc vaccine and CpG in combination with curcumin lavage elicits a protective antitumor response in FAPα-positive B16 tumor-bearing mice." (PMID 26305550, 2015). "Tumor growth was significantly retarded and the lifespan was significantly prolonged in mice vaccinated with FAP-expressing tumor cells compared with the control mice." (PMID 26394925, 2015). "Our results indicated that the whole-cell tumor vaccine modified to express FAP induced strong protective and therapeutic antitumor immunity via CD8+ T-cell-mediated killing." (PMID 26394925, 2015). "This specific immune response was examined further using western blotting, which showed that the anti-FAPα antibody from individual immunized mice recognized FAPα protein in lysates of tumor tissue from B16 tumor-bearing mice." (PMID 26305550, 2015). "This is consistent with the observation that the elimination of FAPα-expressing cells led to stunted tumor growth and enhanced anti-tumor immune response in a mouse model." (PMID 25593080, 2015). "In the peritumoral compartment, FAP expression was predominantly found in adjacent CAFs close to tumor cells, with less expression in the surrounding CAFs." (PMID 25775399, 2015).